ZNF321P (zinc finger protein 321, pseudogene)
Synonyms: MGC35402; formerly ZNF321
Gene: Transcribed processed pseudogene on chromosome 19 (52,928,903 to 52,929,397, reverse strand). Ensembl gene ENSG00000213801.
Diseases named in the same sentence as ZNF321P in open-access papers:
ZNF321P is named in the same sentence as 1 disease in open-access papers, as found by Europe PMC text mining. Sharing a sentence is not in itself a finding about the gene and the disease.
ZNF321P shares sentences with these, for which no sentence is quoted: infection (1 paper).